KDM5B (lysine demethylase 5B)
Diseases named in the same sentence as KDM5B in open-access papers (continued):
Sharing a sentence is not in itself a finding about the gene and the disease.
tumor (153 papers, 2010 to 2026). "Supportively, our study demonstrated that a small molecule inhibitor of KDM5B, AS-8351, effectively restrained the tumor progression of EBV-associated malignant cells in mice." (PMID 40059116, 2025). "Several studies have shown that KDM5B is linked to cancer immunotherapy and that its inhibitor AS‐8351 can suppress EwS cell proliferation and inhibit tumour growth in nude mouse models." (PMID 39643939, 2024). "Clinicopathologic variables were evaluated for association with expression of KDM5B, the expression levels of KDM5B were robustly correlated with tumor size (P = 0.018), TNM staging (P = 0.023), HbA1C (P = 0.043), and TG (P = 0.035), TC (P = 0.028)." (PMID 38789418, 2024). "KDM5B is overexpressed in this type of tumor and is associated with tumor progression and poor prognosis." (PMID 38004468, 2023). "CPI-455 induced dramatic reprograming of the androgen regulated transcriptome in LNCaP including genes associated with cancer pathways, supporting a tumor promoting role for KDM5B in PCa." (PMID 37152294, 2023). "The finding that CSE causes KDM5B activation further implicates that this factor is involved in the promotion of tumor initiation, invasion, and metastasis via epigenetic regulation." (PMID 34769496, 2021). "Univariate analysis indicated that three variables (tumor size, vascular invasion, KDM5B-positivity) were risk factors of HCC." (PMID 30344945, 2018). "Given its association with tumor progression and prognosis of cancer patients, KDM5B was proposed to be a novel target for the prevention and treatment of human cancers." (PMID 27974677, 2017). "Several KDMs, including KDM5B have been implicated in tumor growth, angiogenesis, invasion, metastasis, and more recently, in tumor-related chemoresistance." (PMID 26917489, 2016). "χ2 correlative analysis of the KDM5B expression and clinicopathological parameters revealed significant associations between high KDM5B expression and larger tumor size (p = 0.005)." (PMID 26917489, 2016). "Actually, KDM5B has been implicated in silencing tumor suppressor genes such as BRCA, p21 and TIEG1 through its demethylase activity." (PMID 26911146, 2016). "Interestingly, osteosarcomas showing the presence of KMT2D tumor suppressor loss-of-function mutations were sensitive to KDM5B inhibition." (PMID 40940894, 2025). "Our findings provide new insights into the sophisticated epigenetic mechanisms that EBV harnesses to drive tumor progression and suggest a promising therapeutic strategy targeting KDM5B and its molecular interactions for treating EBV-associated epithelial cancers." (PMID 40059116, 2025). "KDM5B is associated with histone methylation and facilitates continuous tumor growth." (PMID 38818308, 2024). "KDM5B has been detected in metastatic adenocarcinomas and neuroendocrine tumors and is associated with advanced tumors, a poor prognosis, and the viability of tumor cells." (PMID 38004468, 2023). "Moreover, the presence of KDM5B isoforms can contribute to tumor progression, while the RBP2-H1 isoform is linked to poor prognoses and KDM5B reduces intratumoral heterogeneity and is related to oxidative phosphorylation." (PMID 38004468, 2023). "In addition to KMT2D, the authors identified seven more epigenetic regulators in CM cell lines (KDM1A, APOBEC2, HDAC6, KMT2F, SETD4, KAT4, and KDM5B) whose loss accelerates CM tumor progression." (PMID 34575678, 2021). "Dysregulated histone demethylase activity, particularly of KDM5B, as well as diminished H4K20me3 levels have been observed in OS and are associated with increased tumor aggressiveness and resistance to chemotherapy, suggesting their involvement in tumor progression and drug resistance." (PMID 40868849, 2025). "Collectively, these results underscore the critical role of the KDM5B/PLK2 axis in EBV-driven tumor progression and highlight its potential as therapeutic target in EBV-associated epithelial tumors." (PMID 40059116, 2025).
tumor (continued). "Our study further delineates a functional link where KDM5B downregulates PLK2 expression by reducing the H3K4me3 levels at the promoter, thereby activating the PI3K/AKT/mTOR pathway to promote tumor progression in EBV-associated epithelial tumors." (PMID 40059116, 2025). "We further investigate the mechanisms by which EBV induces KDM5B expression and its impact on tumor progression, focusing on histone modifications and key signaling pathways." (PMID 40059116, 2025). "The overexpression of KDM5B correlated with tumor progression and cisplatin resistance in patients with nasopharyngeal cancer." (PMID 40940894, 2025). "In parallel, the pharmacological inhibition of KDM5B using AS8351 was much more potent in reducing KMT2D-depleted xenograft tumor growth." (PMID 40940894, 2025). "Our findings reveal how EBV exploits KDM5B to facilitate tumor progression through epigenetic modifications, specifically highlighting the suppression of tumor suppressors and the downstream signaling pathways." (PMID 40059116, 2025). "The stemness genes highly expressed in the C0 subtype included CTNNB1, CD44, and KDM5B, while in the Normal tissue adjacent to neoplasm group, CTNNB1, CD44, and MYC were highly expressed." (PMID 40616092, 2025). "In contrast, KDM5B overexpression in tumor cells led to enhanced cell proliferation, colony formation, and sphere formation capacities, alongside with increased levels of stemness markers." (PMID 40059116, 2025). "In triple‐negative breast cancer, O‐GlcNAcylation at Ser40 of histone H2A inhibits the histone demethylase KDM5B, thereby promoting tumor proliferation and metastasis." (PMID 41394960, 2025). "To investigate the molecular mechanisms by which KDM5B contributes to tumor progression, we conducted a ChIP-seq analysis to map KDM5B occupancy in HONE1-EBV cells with targeted KDM5B knockdown (using siRNA targeting KDM5B, referred to as si-KDM5B#1/2)." (PMID 40059116, 2025). "This EBV-driven upregulation of KDM5B promotes tumor progression by repressing the tumor suppressor PLK2 through H3K4me3 demethylation, thereby activating the PI3K/AKT/mTOR pathway." (PMID 40059116, 2025). "While KDM5B expression is elevated in all tumor stages compared to normal tissue, early-stage tumors exhibit a slightly higher median expression than advanced-stage tumors." (PMID 40764352, 2025). "Comprehensive gene expression profiling of KDM5B across tumor and normal tissues was evaluated using the GEPIA database." (PMID 40764352, 2025). "Upregulated KDM5B promotes PDAC tumor malignancy, i.e. cancer cells stemness and drug resistance in vitro and in vivo, while KDM5B knockout exerts opposite effects." (PMID 38789418, 2024). "Treatment with CMs from tumour cells activated Hs738 cells, and enhanced IL-8 levels, and KDM5B levels were increased accordingly." (PMID 38862740, 2024). "It has been reported that KDM5B is involved in tumour proliferation, metastasis, and immune evasion." (PMID 38862740, 2024). "We found that tumour cell-derived SRGN increased KDM5B expression in CAFs via interacting with its receptor CD44." (PMID 38862740, 2024). "Overexpression of KDM5B remarkably accelerated the tumor growth of Capan-1 cells and became resistant to gemcitabine." (PMID 38789418, 2024). "KDM5B expression was higher in cancer cells than in adjacent normal cells in immunohistochemical analysis of tumor samples from 176 women with invasive ductal carcinoma." (PMID 38769556, 2024). "KDM5B (Ser1456) phosphorylation catalyzed by CDK1 inhibited tumor stemness genes SOX2 and NANOG expression by reducing the enrichment of KDM5B at their promoters." (PMID 38769556, 2024). "Knockdown of KDM5B reduces the division of 4T1 cells and decreases the proliferation of tumor cells in vivo." (PMID 38769556, 2024). "Serglycin (SRGN) secreted by tumour cells activated the CD44/c-Myc pathway to upregulate KDM5B expression, thereby promoting IL-8 production in CAFs." (PMID 38862740, 2024).
tumor (continued). "At last, the xenograft tumor model revealed that lncRNA HOXC-AS3 knockdown suppressed the growth of CC in vivo by limiting KDM5B expression levels." (PMID 38842683, 2024). "Overexpression of KDM5B accelerated the tumor growth of increased tumor growth and increased the number of Ki67, CD133 positive cells." (PMID 38789418, 2024). "Inspecting transcripts which are upregulated upon IOX5 treatment (and downregulated upon loss of Hif-α) we found increased expression of HIF target genes, including the 2OG-dependent JmjC histone demethylase Kdm5b, a known tumor suppressor in AML33." (PMID 38637657, 2024). "Collectively, these results suggested that tumour cell-derived SRGN promotes IL-8 expression in CAFs via the c-Myc/KDM5B pathway." (PMID 38862740, 2024). "Reducing KDM5B leads to apoptosis and inhibits the migration, invasion, and proliferation of HT-29 tumor cells and increases the trimethylation of H3K4 in the p16/INK4A region, which suppresses the tumor." (PMID 38004468, 2023). "The KDM5B enzyme acts as a transcriptional repressor in tumor suppressor genes, silencing them, and its overexpression leads to drug resistance in certain tumor types." (PMID 38004468, 2023). "The histone lysine demethylase KDM5B is involved in tumor induction, infiltration, and metastasis by controlling the methylation levels of H3K4 in cancer cells, influencing the expression of tumor suppressors and oncogenes." (PMID 36834692, 2023). "Overall, KDM5B emerges as a potential therapeutic target for oncological treatment due to its involvement in tumorigenesis, tumor progression, and resistance to therapy." (PMID 38004468, 2023). "In most of these cases, KDM5B also plays a significant role in metastasis development and tumor cell proliferation, while its silencing reduces cell growth." (PMID 38004468, 2023). "miR-194 and miR-29c reduce KDM5B expression and decrease proliferation and tumor growth, while Helicobacter pylori reduces miR-29c, leading to KDM5B overexpression." (PMID 38004468, 2023). "Lung tumor tissues exhibit high expression of KDM5B, and the decreased expression of KDM5B leads to the slowing down of tumor growth through the E2F/RB1 pathway." (PMID 38004468, 2023). "KDM5B has an ambivalent role in oncogenesis, behaving as an oncogene in some cancer cell lines and as a tumor suppressor in others." (PMID 36697763, 2023). "KDM5B represses the tumor suppressor miRNA let-7e and activates cyclin D1, and KDM5B interacts with EMSY and suppresses miR-31 by demethylating H3K4me3." (PMID 38004468, 2023). "This tumor suppressor role seems specific for KDM5B, since selective inhibition of KDM5A in the same cells causes upregulation of p27 and growth arrest at the G1 phase." (PMID 36697763, 2023). "In silico studies have demonstrated that ETV can inhibit tumor cell proliferation and induce apoptosis by reducing KDM5B expression." (PMID 38004468, 2023). "Further investigations showed that KDM5B accumulated CCNE1 in tumor cells by decreasing the expression of FBXW7, which resulted in the acceleration of G1/S cell cycle phase transition and finally promoted malignant proliferation." (PMID 35428764, 2022). "KDM5B removes H3K4me3 and suppresses let-7e microRNA, which acts as a tumor suppressor to downregulate cyclin D1." (PMID 36509829, 2022). "The depletion of KDM5B causes the de-repression of ERV elements and induces interferon response, leading to tumor regression and induction of adaptive immune memory." (PMID 35455671, 2022). "On the other hand, SETDB1 in tumor cells forms a complex with TRIM28 or acts together with KDM5B that interferes with PD-L1 expression by blocking double-stranded RNA (dsRNA) production through the endogenous retroviral (ERV) pathway." (PMID 36713412, 2022). "Although overexpression of KDM5A and KDM5B in several cancers has been confirmed and their oncogenic pathways have been identified, some studies report on the context-dependent tumor-suppressive roles of KDM5A and KDM5B." (PMID 36509829, 2022).
tumor (continued). "In sum, our results suggest that KDM5B expression dynamics can be limited by exogenous genetic or chemical modulation providing a possibility to manipulate KDM5B-dependent tumor maintenance." (PMID 35650266, 2022). "At present, studies on KDM5B are mainly focused on embryonic development and tumor formation, but few focus on the regulation of adult stem cells." (PMID 35788877, 2022). "Silencing of KDM5B resulted in reduced activity of tumor cells in vivo, as evidenced by increased sensitivity to radiation." (PMID 35333349, 2022). "Over time, KDM5Bhigh cells can promote rapid tumor repopulation with equilibrated KDM5B expression heterogeneity." (PMID 35650266, 2022). "Conversely, KDM5B depletion activates these retroelements, leading to a type I interferon response and tumor rejection." (PMID 35805040, 2022). "To investigate the involvement of KDM5B in GC, we examined KDM5B expression by immunohistochemical staining in tissue microarrays (TMAs) containing collected tumor tissue samples and the matched normal adjacent tissues from 71 GC patients." (PMID 34977006, 2021). "The results showed that up‐regulation of KDM5B increased the size and weight of tumours and accelerated their growth, which was neutralized by oe‐KDM5B + sh‐ITGA6 treatment." (PMID 33829656, 2021). "KDM5B can contribute to tumour cell proliferation through epigenetic repression of tumour suppressor miRs by binding to their promoter regions and by removing the H3K4me3 histone modification associated with transcriptional activation." (PMID 33829656, 2021). "KDM5B was found to mark a slow-cycling subpopulation of tumor cells which is essential for continuous tumor growth and resistance to therapy." (PMID 34575678, 2021). "KDM5B (Lysine Demethylase 5B) encodes a master epigenetic regulator of H3K4 methylation that regulates the expression of several oncogenes and tumor suppressors during carcinogenesis." (PMID 33854980, 2021). "A high expression of KDM5B in clinical samples correlates with a lower differentiation status, tumor size and TNM stage." (PMID 34200849, 2021). "This small molecule compound targets KDM5B which has been shown to have an anti-proliferative effect in hematological and solid cancer cell lines as well as inhibiting tumor growth in a dose-dependent manner in xenograft models." (PMID 34220955, 2021). "HCC patients with KDM5B overexpression had more tumor metastasis, poor prognosis, and significantly shorter overall survival." (PMID 32751840, 2020). "Overall these studies suggest a tumor promoting potential of KDM5B, which is consistent with our observations that it is highly expressed in human PCa and its expression correlates with poor patient survival." (PMID 33245716, 2020). "One of the proposed mechanisms of KDM5B-mediated tumor cell proliferation was by repressing tumor suppressor miRNA let-7e." (PMID 32751840, 2020). "Studies showed that KDM5B is upregulated in certain cancers and plays roles in the transcriptional repression of tumor suppressor genes, such as BRCA1." (PMID 32093041, 2020). "Consistently, our bioinformatics analysis reveals that the KDM5B mRNA levels are upregulated in PCa compared to benign prostate tissues, and correlate with increased tumor grade and poor patient survival, supporting an oncogenic function of KDM5B in PCa." (PMID 33245716, 2020). "Various studies confirm the contribution of KDM5B in various signaling pathways for tumor cell development and migration." (PMID 32751840, 2020). "KDM5B has been proposed as a repressor of tumor suppressor genes via removal of the activating H3K4me3 marks." (PMID 31805991, 2019). "Many studies confirm that KDM5B, as a tumor promoting factor, is involved in the tumorigenesis of multiple tissues." (PMID 30728054, 2019). "For instance, inhibition of KDM5B expression in bladder and lung tumor cells can inhibit tumor suppressor by down regulating E2F/RB pathway related proteins." (PMID 30728054, 2019).
tumor (continued). "We previously reported that a functional interaction between KDM5B and the tumor suppressor, HEXIM1, is required for HEXIM1 inhibition of nuclear hormone receptor activity." (PMID 31776402, 2019). "In particular, KDM5A (JARID1A/RBP2) and KDM5B (JARID1B/PLU1) contribute to cancer cell proliferation, reduce the expression of tumor suppressor genes, promote the development of drug tolerance and maintain tumor initiating cells." (PMID 31060229, 2019). "The results of KDM5B as a tumor promoting gene were consistent with the previous reports of Dai and Fan." (PMID 30728054, 2019). "Here, we found that STING was up-regulated by KDM5 inhibitors in a panel of cell lines, and the expression levels of KDM5B and STING were negatively associated in multiple tumor datasets." (PMID 30080846, 2018). "Knockdown of KDM5B led to up-regulation of tumor suppressor genes including BRCA1, CAV1, and HOXA5 and resulted in an increased level of H3K4me3 at the chromatin region of these target genes." (PMID 27974677, 2017). "Recent studies showed that KDM5B expression was increased in breast, bladder, lung, prostate and many other tumors and promotes tumor initiation, invasion and metastasis." (PMID 27974677, 2017). "Another study showed that PHD1 help KDM5B target downstream genes to mediate demethylation and exert tumor-suppressor functions." (PMID 27974677, 2017). "The expression of KDM5B was related well with tumor size, TNM stage, grade and other clinical indexes in some kinds of cancers, but some were not." (PMID 27974677, 2017). "Next, we will discuss the potential function of KDM5B and its role in the tumor growth, development and progression." (PMID 27974677, 2017). "To further determine the effect of KDM5B knockdown on tumorigenicity in vivo, we performed a subcutaneous xenograft tumor model in nude mice." (PMID 26911146, 2016). "This is suggestive of KDM5B’s ability to enhance tumor cell invasion, facilitate their homing and increase the clonogenicity of KDM5B-expressing cells." (PMID 26917489, 2016). "Through structural and biochemical data, we provide insights into the function of PHD1KDM5B in KDM5B-regulated demethylation and tumor-suppressor gene transcription." (PMID 24952722, 2014). "Deletion of kdm5b inhibits tumor growth in a syngeneic mouse mammary tumor, suggestive of its potential role in tumor development." (PMID 24808866, 2014). "While the precise role of KDM5A and KDM5B in tumor formation remains to be elucidated, recent evidence supports the interesting notion that KDM5B overexpression promotes the growth and survival of cancer “stem cells”." (PMID 25329053, 2014). "The specific recognition of unmodified H3K4 by the PHD1 domain of KDM5B is important for the KDM5B histone demethylase activity in cells and for the transcriptional repression of tumor suppressor genes." (PMID 24952722, 2014). "Similarly, shRNA against KDM5B decreased tumor volume and weight by 60–70% in PDAC mice xenograft, while in combination with gemcitabine, the tumor growth was inhibited much stronger than individually used shKDM5B or gemcitabine." (PMID 40940894, 2025). "First, given that KDM5B is a master histone modifier, additional downstream factors, beyond PLK2, may contribute to KDM5B-induced tumor progression in EBV-associated epithelial malignancies." (PMID 40059116, 2025). "Furthermore, treatment with the KDM5B inhibitor AS-8351 markedly attenuated this signaling activity and exhibited strong anti-tumor effect in both in vitro and in vivo patient-derived xenograft models from EBV-associated tumors." (PMID 40059116, 2025). "Furthermore, P. gingivalis facilitates tumor progression by regulating immune checkpoint molecules B7-H4 and KDM5B." (PMID 40843171, 2025).